AIM2 (absent in melanoma 2)
Diseases named in the same sentence as AIM2 in open-access papers (continued):
Sharing a sentence is not in itself a finding about the gene and the disease.
psoriasis (continued). "In addition to its critical role in the inflammasome and trained immunity, AIM2 has also been implicated in several other ways to modulate skin homeostasis, which might potentially be involved in psoriasis occurrence, development, or recurrence." (PMID 36742336, 2023). "In 2016, an epigenome association study (EWAS) of psoriasis was conducted in the Chinese Han population, and the results showed that three CpG sites (cg17217296, cg17515347, and cg07195224) in the promoter region of AIM2 gene were significantly associated with psoriasis." (PMID 36118867, 2022). "Interestingly, AIM2 gene was positively associated with the therapeutic efficacy of Brodalumab and negatively associated with Ustekinumab treatment response, which provide novel clues for clinical decisions on treatment for psoriasis." (PMID 36118867, 2022). "Mutations in genes encoding proteins involved in this regulation might contribute to lower the cytosolic DNA detection threshold required for caspase-1 activation possibly leading to auto-inflammatory syndromes such as psoriasis, which is associated with AIM2 inflammasome activation." (PMID 23630667, 2013). "In inflammatory skin diseases such as psoriasis and atopic dermatitis, AIM2 and NLRC4 are overexpressed in skin lesions, suggesting a common inflammasome expression profile during skin inflammation." (PMID 40431153, 2025). "In keratinocytes affected by psoriasis, the build-up of cytoplasmic DNA activates the AIM2 inflammasome, resulting in the secretion of IL-1β and fostering T-cell-mediated skin inflammation." (PMID 40343299, 2025). "In another study, the AIM2 inflammasome was expressed in the entire epidermis of both the healthy and lesional skin of the AD and psoriasis patients." (PMID 40006996, 2025). "To explore the role of AIM2 in the clinical cutaneous manifestations of psoriasis, we began by analyzing circulating cell-free mtDNA levels in patients with psoriasis." (PMID 39352743, 2024). "We next evaluated AIM2 expression using immunofluorescence by confocal microscopy in the skin of patients with psoriasis and IMQ-treated mouse skin." (PMID 39352743, 2024). "Subsequently, WGCNA showed the hub genes (e.g., S100A12, CYCS, NOD2, STAT1, HSPA4, AIM2, MAPK7), which were significantly associated with clinical phenotype, PANoptosis signature, and identified immune response in psoriasis." (PMID 38125299, 2024). "Collectively, these findings demonstrate that AIM2 is highly expressed in the skin of patients with psoriasis and mice following IMQ treatment." (PMID 39352743, 2024). "We found elevated levels of mitochondrial DNA in patients with psoriasis, along with high expression of AIM2 in both the human psoriatic epidermis and a mouse model of psoriasis induced by topical imiquimod (IMQ) application." (PMID 39352743, 2024). "We next analyzed a public GEO database (GSE117468) to assess the relative expression of AIM2 mRNA in lesioned skin biopsies from patients with psoriasis who were treated with brodalumab, a human monoclonal antibody targeting the receptor subunit IL-17RA." (PMID 39352743, 2024). "In previous studies, elevated expression of AIM2 and Caspase-1 has been observed in rheumatoid arthritis, systemic lupus erythematosus, Sjogren’s syndrome, and psoriasis." (PMID 39100670, 2024). "Here, we found a high expression of AIM2 in both the human psoriatic epidermis and a mouse model of psoriasis induced by topical IMQ application." (PMID 39352743, 2024). "One study found that AURKA is highly expressed in psoriasis tissues and can promote the occurrence of psoriasis-related inflammation by blocking the autophagy-mediated AIM2 inflammasome." (PMID 39045407, 2024). "Our data indicate that AIM2 is predominantly expressed in the epidermis of the lesioned skin of patients with psoriasis or mice undergoing the IMQ-induced psoriasis model." (PMID 39352743, 2024). "Collectively, our data show that AIM2 is involved in developing psoriasis through its canonical activation." (PMID 39352743, 2024).
psoriasis (continued). "Strikingly, AIM2 mRNA levels in injured psoriasis skin increased as compared with normal and uninjured psoriasis skin." (PMID 39352743, 2024). "Consistent with data from patients with psoriasis, we found that Aim2 mRNA increased significantly in the skin of mice, particularly on days 2 and 3, following topical IMQ application." (PMID 39352743, 2024). "Genetic ablation of AIM2 reduced the development of IMQ-induced psoriasis by decreasing the production of type 3 cytokines (such as IL-17A and IL-23) and infiltration of immune cells into the inflammatory site." (PMID 39352743, 2024). "Next, we sought to investigate the pathophysiological relevance of AIM2 expression to establish psoriasis-like skin inflammation." (PMID 39352743, 2024). "Accordingly, we found a significant increase in AIM2 expression within the epidermis of lesioned skin in human psoriasis and in psoriasiform skin inflammation induced by the topical application of imiquimod (IMQ) in mice." (PMID 39352743, 2024). "Together, these findings suggest the role of the AIM2 inflammasome pathway in triggering skin inflammatory responses observed during psoriasis." (PMID 39352743, 2024). "Beyond the brain, reduced AIM2 levels correlate with prostate and colorectal cancer development, and increased AIM2 expression is associated with SLE and psoriasis." (PMID 39704565, 2024). "Although researchers found that AIM2 is expressed only in the Langerhans cells and melanocytes of healthy skin, AIM2 can be upregulated significantly in keratinocytes when skin suffers from harmful conditions such as psoriasis or wounds." (PMID 36742336, 2023). "Chou’s finding attracted us to believe that regulation of Treg cell function through AIM2 can mediate the pathogenesis of psoriasis or other inflammatory diseases." (PMID 36742336, 2023). "IFN-β produced by cGAS-STING pathway also can activate the JAK-STAT pathway, cross-link AIM2 inflammasome and these signaling pathways, mediate the development of psoriasis together." (PMID 36742336, 2023). "To explore the in vivo relevance of the inhibitory effect of CO on AIM2 inflammasome activation in cells, we investigated the effect of CO on skin inflammation in an imiquimod-induced psoriasis mouse model." (PMID 36982727, 2023). "When keratinocytes are infiltrated with proinflammatory cytokines such as IFN-γ and TNF-α, AIM2 inflammasome activation and downstream IL-1β release have been proven to result in psoriasis lesions." (PMID 36742336, 2023). "For example, in psoriasis-a chronic autoimmune-mediated inflammatory skin disease-cytosolic DNA induces IL-1β release from keratinocytes via an AIM2-dependent inflammasome." (PMID 36680007, 2023). "Prior studies showed that excessive cytosolic DNA can trigger AIM2 inflammasome activation in keratinocytes in psoriatic lesions and contribute to the progression of psoriasis." (PMID 36982727, 2023). "We examined the inhibitory effects of Cornus officinalis seed extracts on AIM2 inflammasomes and its mechanisms of action within cells, as well as its in vivo efficacy in an imiquimod-induced psoriasis model." (PMID 36982727, 2023). "In psoriasis, IL-1β is mediated by an apoptosis-associated speck-like protein containing a caspase recruitment domain, such as NLRP3 and AIM2." (PMID 37465147, 2023). "Epidermal AIM2 mRNA and protein expression are upregulated in skin diseases, including psoriasis, atopic dermatitis, venous ulcers, and contact dermatitis." (PMID 37443800, 2023). "In this review, we will elaborate on the characteristics of AIM2 and how AIM2 mediates the development of psoriasis." (PMID 36742336, 2023). "Some studies suggest that the AIM2 inflammasome activation is contributed to by the progression of psoriasis by the release of pro-inflammatory cytokines." (PMID 36982727, 2023). "In psoriasis, NETs activate AIM2 inflammasome through the p38 MAPK signaling pathway, thus causing the production of IL-1β." (PMID 37187738, 2023).
psoriasis (continued). "Studies will be needed to explore the correlation between epigenetic regulation and AIM2 gene expression in the future and to further clarify its regulating effect in the pathogenesis of psoriasis." (PMID 36118867, 2022). "The further therapeutic effects of RGFP966 on psoriasis by regulating the AIM2 inflammasome will be investigated in the future." (PMID 36118867, 2022). "An in vivo study demonstrated significantly augmenting protein expression of AIM2 in IMQ-induced psoriasis-like mouse model." (PMID 36110207, 2022). "Psoriasis has a high levels of AIM2, the activation of which initiates the assembly of the inflammasome, triggering the maturation and secretion of the cytokine IL-1β (Lugrin and Martinon, 2018, 2)." (PMID 36110207, 2022). "AIM2 inflammasome activation has also been shown in diseases such as psoriasis, atherosclerotic lesions, or cardiovascular diseases that have ocular manifestations or serve as risk factors for AMD." (PMID 35883779, 2022). "In this review, we summarized the roles of the AIM2 gene and AIM2 inflammasome in pathogenesis and treatment of psoriasis, hopefully providing a better understanding and new insight into the roles of AIM2 gene and AIM2 inflammasome in psoriasis." (PMID 36118867, 2022). "One study revealed that inflammasome sensors, NLRP3, NLRP1, CASP1, and AIM2, enhanced expression in psoriasis patients." (PMID 36110207, 2022). "Lupus patients including DLE and SLE, exhibited significantly higher frequencies of AIM2+ TFH‐like cells than psoriasis patients and NCs." (PMID 35343082, 2022). "Inflammasome genes are highly upregulated in psoriatic epidermis and the evidence collected here points out the roles of AIM2 an NLRP3 in the pathogenesis of psoriasis and its systemic manifestations." (PMID 34502368, 2021). "elaborated on the role of AIM2 inflammasomes in cancer and autoimmunity, that inappropriate recognition of cytoplasmic self-DNA by AIM2 contributes to the development of psoriasis, dermatitis, arthritis, and other autoimmune and/or inflammatory diseases." (PMID 34925345, 2021). "In this systemic review, we collect recent and comprehensive evidence from the inflammasomes, NLRP1, NLRP3, and AIM2, in pathogenesis of psoriasis." (PMID 34072753, 2021). "After activation, AIM2 assembles inflammasome, driving IL-1β secretion and contributing to psoriasis." (PMID 33681365, 2021). "The databases were searched using the terms “inflammasome”, “NLRP1”, “NLRP3” or “AIM2” and “psoriasis” or “psoriatic arthritis”." (PMID 34072753, 2021). "In cultured keratinocytes, AIM2 and cytosolic DNA triggered the release of IL-1β, therefore indicating that cytosolic DNA can trigger AIM2 inflammasome and IL-1β activation in psoriasis." (PMID 34502368, 2021). "Recently, Chung reported that red vine leaf extract (EFLA 945) greatly attenuated IMQ-induced psoriasis phenotypes by inhibiting the activity of the AIM2 inflammasome." (PMID 32528469, 2020). "Cytosolic DNA triggers the activation of the AIM2 inflammasome and IL-1β in psoriasis; LL-37 blocks AIM2 inflammasome activation." (PMID 32528469, 2020). "In psoriatic patients, the expression of AIM2 and IL-1β is increased in keratinocytes from the skin lesion, and the activation of AIM2 in cultured keratinocytes leads to IL-1β release, suggesting that AIM2 is involved in the psoriasis pathogenesis." (PMID 32295112, 2020). "The levels of AIM2 were found to be increased in keratinocytes derived from psoriasis and AD patients, which led to acute and chronic skin barrier disruption-related inflammation." (PMID 32528469, 2020). "In this study, we investigated the role of AIM2 in the pathophysiology of psoriasis." (PMID 39352743, 2024). "Furthermore, AIM2 signaling exacerbates the pathophysiology of IMQ-induced psoriasis–like skin inflammation." (PMID 39352743, 2024).
psoriasis (continued). "Since IL-17A is a crucial mediator in the pathogenesis of psoriasis, inducing the proliferation and secretion of inflammatory mediators by KCs, we next investigated whether IL-17A could modulate AIM2 expression in KCs." (PMID 39352743, 2024). "Therefore, our findings provide insights regarding the development of psoriasis and strengthen the potential of formulating drugs targeting AIM2 as a new therapeutic strategy for clinical psoriasis management." (PMID 39352743, 2024). "Therefore, our study demonstrates the critical role of the AIM2-dependent inflammasome in the pathogenesis of skin psoriatic inflammation and proposes AIM2 as a promising therapeutic target for psoriasis." (PMID 39352743, 2024). "The inflammation-related gene absent in melanoma 2 (AIM2) was identified as a susceptibility gene/locus associated with psoriasis." (PMID 39352743, 2024). "Moreover, AIM2 expression is increased in KCs from skin lesions of patients with psoriasis, and its activation in cultured KCs leads to IL-1β release, suggesting that AIM2 is involved in the pathogenesis of psoriasis." (PMID 39352743, 2024). "Together, these studies and our findings suggest that dsDNA may activate AIM2 in KCs, promoting the development of psoriasis." (PMID 39352743, 2024). "In individuals with psoriasis, neutrophil extracellular traps (NETs) not only activated AIM2 inflammation via traditional signaling pathways but also induced the AIM2 inflammasome through the p38/MAPK signaling cascade in a manner independent of dsDNA, resulting in the production of IL-1β." (PMID 39600708, 2024). "In addition, there are some studies on pyroptosis-related proteins upstream of GSDMD, such as NLPR3 inflammasome and AIM2 inflammasome, which are involved in and promote psoriasis through downstream inflammatory cytokines." (PMID 39717896, 2024). "We finally investigated whether the AIM2 function depends on inflammasome components during psoriasis." (PMID 39352743, 2024). "AIM2 inflammasome is necessary for the induction of psoriasis-like skin inflammation." (PMID 39352743, 2024). "With all that in mind, we can speculate that AIM2 might be the key marker modulating trained immunity in epidermal keratinocytes, as well as an important factor leading to the relapse of psoriasis, which needs more evidence for verification." (PMID 36742336, 2023). "Does the AIM2 inflammasome-induced trained immunity link to psoriasis recurrence?" (PMID 36742336, 2023). "Absent in melanoma 2 (AIM2), a susceptibility gene locus for psoriasis, has been strongly linked to the genetic and epigenetic aspects of psoriasis and increased in expression in psoriatic keratinocytes." (PMID 36742336, 2023). "The AIM2 inflammasome is an innate immune system component that defends against cytosolic bacteria and DNA viruses, but its aberrant activation can lead to the progression of various inflammatory diseases, including psoriasis." (PMID 36982727, 2023). "Roles of AIM2 gene and AIM2 inflammasome in the pathogenesis of psoriasis." (PMID 36118867, 2022). "However, Fra-1 needs to be further investigated on how it regulates the expression of AIM2 in psoriasis, which is still unclear." (PMID 36118867, 2022). "The roles of AIM2 gene in the pathogenesis of psoriasis have been studied." (PMID 36118867, 2022). "Finally, the qRT-PCR results demonstrated the apparent dysregulation of PRGs in psoriasis, especially AIM2 and GZMB." (PMID 36110207, 2022). "Recent studies have found that certain factors regulate the AIM2 inflammasome signaling pathway and participate in the pathogenesis of psoriasis, including prokineticin 2 (PK2), caspase recruitment domain family member 18 (CARD18), aurora kinase A (AURKA), TLR-7, TLR-8, and TLR-9 antagonists." (PMID 36118867, 2022). "Thus, PK2 regulates the AIM2 inflammasome signaling pathway involved in the pathogenesis of psoriasis." (PMID 36118867, 2022).
psoriasis (continued). "AIM2 response to dsDNA and then induce AIM2-dependent release of IL-18 and IL-1β, which plays a critical role as a trigger of autoimmune diseases, including psoriasis, systemic lupus erythematosus, primary Sjogren’s syndrome." (PMID 36118867, 2022). "Currently, further research is needed to determine whether WFA can affect the occurrence and progression of psoriasis by inhabiting the AIM2 inflammasome pathway." (PMID 36118867, 2022). "AIM2 gene has an essential role in the occurrence and development of psoriasis, and the inhibitors of AIM2 inflammasome will be new therapeutic targets for psoriasis." (PMID 36118867, 2022). "The inflammation-related gene absent in melanoma 2 (AIM2) was identified as a susceptibility gene for psoriasis." (PMID 36118867, 2022). "In addition, AIM2 inflammasomes are closely related to human diseases, such as psoriasis and systemic lupus erythematosus, which are all related to the increased expression of AIM2." (PMID 35132346, 2022). "It is worthy to further investigate whether AIM2 expression can be a biomarker to distinguish different subtypes of psoriasis." (PMID 36118867, 2022). "AIM2 expression is increased in patients with systemic lupus erythematosus (SLE), psoriasis, and primary Sjogren's syndrome, indicating that AIM2 might be involved in the pathogenesis of autoimmune diseases." (PMID 34014039, 2021). "Cathelicidin LL-37 can interact with DNA and is highly expressed in psoriasis; it is hypothesized that LL-37–DNA interactions may contribute to activation of AIM2 dependent inflammasome." (PMID 34072753, 2021). "This suggests that untreated psoriasis levels of LL-37 may be insufficient at inhibiting the activity of the AIM2 inflammasome." (PMID 34072753, 2021). "In this work, AIM2 expression was positively correlated with M1 macrophage fraction in psoriatic plaque, indicating that AIM2 might regulate psoriasis progression through modulating M1 macrophages." (PMID 33681365, 2021). "Reaffirming the role of inflammasomes as a potential therapeutic target in the treatment of psoriasis, as with the NLRP3 inflammasome, researchers focused on finding substances that would silence or completely inhibit AIM-2 inflammasome activation in psoriasis." (PMID 34072753, 2021). "Moreover, the AIM2 inflammasome in keratinocytes also supports the development of psoriasis in humans, and even NLRP3 variants seem to play a role in psoriasis susceptibility." (PMID 32053878, 2020). "Koning showed that AIM2 is expressed exclusively in Langerhans and melanocyte cells in normal epidermis, but is significantly upregulated in keratinocytes under inflammatory conditions such as psoriasis, AD, and allergic contact dermatitis." (PMID 32528469, 2020). "Moreover, the AIM2 inflammasome plays an important role in psoriasis, a common inflammatory skin disease, as cytosolic DNA triggers AIM2 inflammasome activation in HPKs and in lesion of patients suffering from the disease." (PMID 32640751, 2020). "Interestingly, while LL-37 serves as an autoantigen in psoriasis immunopathogenesis, studies suggest that it can also inhibit AIM2-mediated inflammasome formation." (PMID 31130981, 2019). "Hence, cytoplasmic DNA appears to contribute to the pathogenesis of psoriasis via activation of IL-1β in keratinocytes by AIM2-mediated inflammasomes." (PMID 31877866, 2019). "AIM2 activation has been reported during infection with cytosolic bacteria or DNA viruses as well as during autoinflammatory syndromes such as psoriasis." (PMID 23630667, 2013). "In this review, we focus on the characterization of AIM2 and its relationship with psoriasis, how AIM2 plays an inflammasome-dependent and possibly inflammasome-independent role in the development of psoriasis, and how AIM2 may potentially modulate psoriasis relapse by training immunity." (PMID 36742336, 2023).